CD4 (CD4 molecule)
Diseases named in the same sentence as CD4 in open-access papers (continued):
Sharing a sentence is not in itself a finding about the gene and the disease.
infection (continued). "We also analyzed the proliferation of CD4+ T cells based on the expression of Ki67 and found that LAG3+CD4+ T cells proliferated more than LAG3-CD4+ T cells after 24 weeks of infection." (PMID 37172058, 2023). "Cluster T13 was increased after infection, with a low expression of Cd4 and high expression of Tcrg-c1, presumably as γδT cells." (PMID 37039643, 2023). "In a subset of matched infection-naïve cases and controls, vaccine breakthrough cases had lower CD4+ and CD8+ IFNγ and tumor necrosis factor (TNF) responses to Delta S peptides compared with controls." (PMID 37655880, 2023). "Removal of IFNAR1 from CD11c+ or CD4+/CD8+ T cells caused an increase in the titer of viruses, which persisted throughout the infection." (PMID 37766322, 2023). "Depletion of CD4+ T cells in the mice significantly improved the condition of the mice during infection, indicating that a biased Th2-type immune response contributes to disease severity in FI-RSV-vaccinated mice." (PMID 37896776, 2023). "In male mice, during acute infection, the levels of CD4+ cells and CD8+ significantly increased in MFD-fed infected mice compared to RD-fed infected mice as demonstrated by Western blotting analysis." (PMID 36676177, 2023). "Upon vaccination with the LAV, IMs expressed T cell chemoattractant CXCL9 that attracted CD4+ T cells to the foci of infection, where IMs also served as a potent source of antigen presentation and Th1-promoting cytokine IL-12." (PMID 37733817, 2023). "Together our data suggest that IMs play an important role in recruiting CD4+ T cells to the foci of infection via the CXCL9/CXCR3 axis and provide an important source of IL-12 for maintaining Th1 cells." (PMID 37733817, 2023). "Another study employed similar methods for the activation of CD4+ T cells, followed by their infection with HIV-1NL4-3 and HIV-1 NLENG1-IRES." (PMID 37513726, 2023). "CAST/EiJ mice were protected from mortality by IL-15 therapy when CD8+ and CD4+ T cells were eliminated prior to infection with MPOX." (PMID 37533932, 2023). "The mice receiving PBS or serum had comparable high bacterial loads in the BAL fluid at day 2 after 86-028NP infection, whereas mice receiving adoptively transferred CD4+ T cells had 2-log lower bacterial burdens." (PMID 36736665, 2023). "Using well-established animal models of infection and immunity, it was revealed by depletion experiments that both the CD4+ and CD8+ T lymphocytes were necessary to generate the LST response." (PMID 37919280, 2023). "Because TB antigen-specific CD4+ T cells are recruited to the infection site, PF is richer in antigen-experienced T cells than matched PB." (PMID 37809012, 2023). "A similar pattern of infection was obtained when MDM infection was mediated by HIV+ autologous primary CD4+ T cells." (PMID 36988579, 2023). "We found that BA.1 breakthrough infection efficiently induced spike specific CD4+ T cells and CD8+ T cells." (PMID 37037791, 2023). "There was a significant statistical difference between the Bh infection and different CD4+ T cell counts (χ2 = 71.388, P < 0.001)." (PMID 37697423, 2023). "Since CD4 T cells are such an important part of the acquired immune response, they guard against infection while simultaneously supporting the formation of mononuclear lesions and the caseous necrosis necessary for transmission." (PMID 37111338, 2023). "In our study, down-regulation of CD4 was observed in AS and koi strains during both genogroup I or IIa infections at days 6 and 11 post-infection compared to the control group." (PMID 37465154, 2023). "Cotransfer of Fo B with CD4+ T cells inhibited the ability of CD4+ T cells to protect against infection." (PMID 37721965, 2023). "Cxcr3 is located on the X chromosome, and during inflammation is upregulated on macrophages, dendritic cells, and CD8+ and CD4+ T cells, promoting their migration to sites of infection." (PMID 37063266, 2023).
infection (continued). "CCl20 and its receptor, CCR6, control the migration of dendritic cells and Th17 CD4+ T cells to the site of infection and inflammation." (PMID 37243277, 2023). "Knockout of UBE2M in Jurkat cells exhibited the most potent inhibition of infection of all the validated genes except for the positive control, CD4." (PMID 36744886, 2023). "In HIV infection, ADE allows rapid viral trafficking by antigen presenting cells (e.g., macrophages) to lymph node resident CD4+ T cells following mucosal transmission, enhancing early processes required to establish robust infection." (PMID 37744365, 2023). "B-cell cellularity remained similar throughout the infection, and CD4+ and CD8+ T lymphocytes increased modestly with a significant contribution of ESX-1." (PMID 37017530, 2023). "We also examined the Tr1 cell–associated transcription factor PBX1 and found that it suppressed proinflammatory cytokine production by activated CD4+ T cells at sites of infection and inflammation." (PMID 37917177, 2023). "Viral transmission from infected CD4+ T cells to macrophages during engulfment accounts for a small fraction of macrophage infection." (PMID 37476291, 2023). "CD4+ T-cell levels <300/μL and CD4+ T-cell levels ≥ 300/μL were found to have a significantly different effect on the overall probability of having an early infection (P = 0.0013)." (PMID 37360336, 2023). "The infection with Mtb increases CD4+TNF-α+, CD4+IFN-γ+, and CD4+IL-17+ in the lymph nodes of rBCG-LTAK63 immunized animals, while in the lungs, there was a drastic difference in CD4+IFN-γ+, and CD4+IL-17+, when compared with BCG." (PMID 37520577, 2023). "Th1 cells, which differentiate from CD4+ T cells, secrete cytokines that play critical roles in combating infections." (PMID 38093398, 2023). "CD4+ cells are critical for the deterrence of primary infection, whereas CD8+ cells are role players during the secondary immune response." (PMID 37265481, 2023). "Cathepsin L also plays a role in antigen processing, suggesting that only the non-permissive mice are able to process exogenous proteins effectively during infection prior to the activation of CD4 + T cells." (PMID 36883013, 2023). "The increase in explained variance for the rate of disease progression makes us believe that including the CD4+ T cell count after primary infection results in a measure of virulence that is more predictive of the observed time until disease." (PMID 37161335, 2023). "In most cases, the addition of anti-IL-6 antibody reduced the infection rates to the level of unstimulated resting CD4 + T cells, suggesting that IL-6 was necessary for the effect of IEC stimulation." (PMID 37202790, 2023). "CD4 T lymphocytes are the primary targets for infection and viral reservoirs, and cytolytic CD8 T cells and natural killer (NK) cells play key roles in eliminating HIV-1-infected cells (8, –, 10)." (PMID 37874153, 2023). "Overall, the data suggest that Bhlhe40 negatively regulates IL-10 production in the spleen after infection with P. yoelii and that splenic antigen-specific CD4+ T cells contribute to the elevated IL-10 production in the absence of Bhlhe40." (PMID 37843306, 2023). "TNF-α and/or IFN-γ-producing VP6-specific CD4+ T cells were rarely detected in children presenting with or without rotavirus diarrhoea at both acute and convalescent phases of infection, with frequencies mostly below 0.01%." (PMID 37268634, 2023). "We demonstrate that in the absence of SARS-CoV-2-specific CD8 T-cell, the significant reduction in viral load observed at day 8 post infection is largely mediated by CD4 T-cells." (PMID 38150441, 2023). "Our more detailed findings using ICS support a role for both CD4+ and CD8+ T cells in protecting against susceptibility to overt infection with the Delta variant." (PMID 37655880, 2023). "During the acute stage of infection, a smaller proportion of CD4+ T cells from TfrcY20H/Y20H mice expressed B cell co-stimulation receptor ICOS." (PMID 37812650, 2023).
infection (continued). "Although humoral immunity mediated by antibodies blocks SARS-CoV-2 from entering host cells and thus prevents infection, specific CD4+ and CD8+ T cells appear to be responsible for limiting disease severity." (PMID 36852582, 2023). "For CRF01_AE, only the baseline CD4+ T cell count was lower (p = 0.0315) in the X4-tropic infection." (PMID 37152735, 2023). "This contrasts with the data described herein, where one dose of BNT162b2 was sufficient to induce an increase in S-specific CD4+ T cells in infection-naive adolescents." (PMID 37942333, 2023). "To mimic a natural situation, we used two time points:treatment with CD4-PP at the start of infection or two hours postinfection.In addition, we utilized two cell types which are present in wounds:keratinocytes and resident macrophages." (PMID 37132993, 2023). "Irf4-/- mice showed reduced accumulation of CD4+ T cells in the colon, both under homeostatic conditions and after infections." (PMID 37469513, 2023). "We then co-cultured HIV-1-R5-infected siRNA-treated MoDC with autologous CD4+ T lymphocytes in order to analyze the transmission of infection." (PMID 37240354, 2023). "Infection of CD4+ T lymphocytes (TCD4+) is a critical step in HIV transmission and appears to occur via a two-step mechanism." (PMID 37243118, 2023). "μMT mice also displayed ~30% increase in T-bet expression on CD44+CD4+ T cells one week post infection, though this difference dissipated two weeks post challenge." (PMID 37721965, 2023). "It is proposed that CD4+ T cell activation during MHV68 infection is mediated by uninfected myeloid cells that present MHV68-derived peptides loaded on MHC class II." (PMID 37065193, 2023). "Memory CD4+T cells closely coordinate with B cells following infection and/or vaccination, sustaining protective immunity 13–15." (PMID 37173361, 2023). "Accordingly, we found that viral shedding in the saliva and viral replication in the SGs were reduced in Cd4Cre/+Arg1flox/flox versus Cd4+/+Arg1flox/flox mice during the chronic phase of infection with MCMV." (PMID 37440306, 2023). "Before 2011, they began ART when they presented with advanced HIV clinical infection (WHO clinical stage 3 or 4) or a CD4 count ≤ 200 cells/mm3." (PMID 36828530, 2023). "Above all, several variables showed potential associations (P < 0.20) with Bh infection among PLWH by univariate analysis, including family members, newly infection, CD4+ T immunological status, HIV virological status, and treatment interruption." (PMID 37697423, 2023). "We found IEC (both + and −) induced significantly higher levels of infection than resting CD4 + T cells alone (p < 0.0001)." (PMID 37202790, 2023). "In contrast to CD8+ T cells, where Eomes is readily found and induced during an acute infection, Eomes induction in CD4+ T cells requires particular models, which has hampered a thorough understanding of its role." (PMID 36756120, 2023). "We discovered and report here that productively and latently infected cells can instead originate from direct infection of resting CD4+ T cell populations in lymphoid tissues in Fiebig I, the earliest stage of detectable HIV infection." (PMID 37733443, 2023). "After clearance of infection, a small percentage of CD4+, CD8+ T cells and B cells will become memory cells, with a transition back to a quiescent mitochondrial-dependent state, establishing immunological memory to the previously terminated foreign pathogen." (PMID 37239997, 2023). "We conclude that GPI-scFv X5 on the surface of transduced CD4+ T cells not only potently blocks cell-mediated infection by DCs, but it transfers from transduced cells to the surface of iDCs and neutralizes HIV-1 replication in iDCs." (PMID 37781368, 2023). "In fact, HIV-1 trans-infection from DCs or B cells to autologous CD4+ T cells is reduced by 60% and 90%, respectively, following lovastatin treatment." (PMID 38140588, 2023).
infection (continued). "CD4+ T cells contribute to the control of infection by facilitating B cell and CD8+ T cell activation and secreting cytokines." (PMID 37055751, 2023). "Progressors, on the other hand, rapidly lose their NAb response during the course of their infection due to a rapid decline in CD4+ T-cell density." (PMID 37376660, 2023). "Infection by the oral route also requires MMTV replication in proliferating CD4+ lymphocytes using a vSAG-dependant mechanism in the gastrointestinal tract." (PMID 36869359, 2023). "This would be expected since CD4 T cells are critical to facilitate the antibody response to infection." (PMID 37841265, 2023). "We used this pipeline to sort and sequence TCRs specific for 3 CD8+ and 1 CD4+ LCMV epitopes from mice at day 8 post-infection." (PMID 37325645, 2023). "We next assessed the impact of natural infection before vaccination on the dynamics of the SARS-CoV-2-specific CD4+ T cell response." (PMID 37575243, 2023). "After infection with B. contaminans, CD4+ or CD8+ T cells isolated from blood of cows produce hardly any IFN-γ." (PMID 36960295, 2023). "There was no significant influence of prior B-cell–depleting therapy in the pre- and post–BT infection frequency of activated CD4+ or CD8+ T cells." (PMID 38023562, 2023). "It is believed that infiltrating CD4+ T-cells and perivascular macrophages facilitate infection of proximal microglia, trafficking macrophages, and astrocytes, and HIV-infected CD4+ T-cells and macrophages as well as cell-free virus are present in CSF." (PMID 38140626, 2023). "We therefore quantified the infection frequency of intact p24 per 106 cells within the four CD4+ T-cell subsets." (PMID 36776833, 2023). "The baseline CD4+ T cell count (p < 0.0001) and baseline CD4+ T/CD8+ T ratio (p = 0.0006) of all R5-tropic infections were higher than those in the X4-tropic infection." (PMID 37152735, 2023). "Virus levels are extremely low in subclinical infections, yet both CD4+ and CD8+ T cell responses to human CMV (HCMV) antigens comprise, on average, ~10% of circulating memory T cells." (PMID 36749635, 2023). "The contemporaneous presence of high levels of CD4+ T-cell activation and high levels of viremia leads to further new infection and consequent death of CD4+ cells." (PMID 36672667, 2023). "Such increase of infection would probably contribute significantly to the infection and massive depletion of CD4 + T cells in the gut mucosal area during primary HIV infection." (PMID 37202790, 2023). "Induction of IFN-γ secreting CD4+ T cells was shown to contribute to host survival and recovery after infection, supporting a possible role of T cell immunity in cross-protection." (PMID 37170231, 2023). "Throughout the infection, PD-1+ cells were observed in dLNs, in addition to an enhanced expression of PD-1 in both CD4+ and CD8+ T lymphocytes." (PMID 37691941, 2023). "Cell-mediated immunity, and particularly CD4 Th1 cells, play a major role in both primary and reinfection: during the early stage of infection, ORFV induces a vigorous inflammatory response, leading to tissue damage and consequent viral clearance." (PMID 37317112, 2023). "It is likely that CD4+ T cell responses were impaired during infection with Cn H99, plb1, or Rec1 due to the baseline levels of IFN-γ detected in the supernatants of brain homogenates." (PMID 36786559, 2023). "If so, the activation of IL-2Rα on APC by PR pathways is another mechanism by which infection-stimulated PR pathways contribute to CD4 memory generation." (PMID 38152398, 2023). "IL-17A-producing CD4 Th17 cell-dependent immunity is important for protection against infections with single Sp infection." (PMID 37222516, 2023). "The Armstrong strain of LCMV is cleared by eight days post-infection, which corresponds to a strong expansion of CD4+ and CD8+ virus-specific T cells." (PMID 37325645, 2023).
infection (continued). "Pyroptotic CD4+ T cells in lymphoid organs was shown through in vitro models to release pro-inflammatory cytokines, inducing a local inflammation that further recruits new CD4+ T cells to the site of infection." (PMID 36800238, 2023). "Further investigation revealed that Arg1 expression was a critical immune regulatory function of CD4+ T cells, suppressing antiviral immunity and facilitating viral chronicity in the context of infection with MCMV." (PMID 37440306, 2023). "About 30% of lung-infiltrating CD4+ T cells produced IL-17 in 4 or 8 week-old 6.5 mice on day 7 after the infection with 2.5 × 103 p.f.u. of PR8 influenza virus." (PMID 37270623, 2023). "Our results are in line with results of Minutti, where infection of mice with H. polygyrus resulted in an increased number of CD4+ T cells with EGFR expression in duodenum, MLN, and spleen." (PMID 36836678, 2023). "Nearly a dozen of these are now in clinical use, and most demonstrate high efficiency in terms of protection and induce an immune response closely resembling that induced by infection in terms of immunophenotype, magnitude of CD4+ response and antibody levels." (PMID 37020560, 2023). "Infection of BMDCs also led to increased in vitro stimulation of CD4+ and CD8+ T cells from splenocytes collected from previously infected female mice." (PMID 38441219, 2023). "Taken together, these data indicate that GPI-scFv X5 significantly blocks iDC or mDC-mediated trans-infection of CD4+ target cells by HIV-1." (PMID 37781368, 2023). "Here, we first report the presence of PvDBPII-specific IFN-γ memory CD4+T cells along with their corresponding subsets following natural infection." (PMID 37173361, 2023). "For a long time during HAART (from the initiation to the 3000th day of HAART), the CD4+ T cell count was higher in CRF07_BC, indicating that the overall immune level of infections with CRF01_AE was lower during early-stage HAART." (PMID 37152735, 2023). "Using a dedicated TALEN, our group showed high-efficiency CCR5-knockout and protection of gene-edited CD4 T cells from infection with CCR5-tropic lentiviral vectors and replication-competent CCR5-tropic HIV-1-BaL strains." (PMID 37511168, 2023). "An increase in CD4+ lymphocytes was observed in both groups at day 4 post-infection, including a significant increase (p < 0.0001 for both younger and older hamsters) from levels of circulating CD4+ lymphocytes at day 1 post-infection." (PMID 37242338, 2023). "Three months after infection, we observed higher levels of basophils, and after 6 months, higher CD4/CD8 ratios and T cell levels in the severe compared to non-severe group." (PMID 37893102, 2023). "This perspective proposes an additional model, suggesting that HIV-1 latency established in activated CD4 T-cells shortly after infection ensures greater survival capacity and possibly a return to a resting memory state." (PMID 38093984, 2023). "AIM+ CD4+ T-cell frequencies increased with time since infection, whereas AIM+ CD8+ T-cell expansion was greater after recent reinfection." (PMID 37220145, 2023). "Our results showed that EOS (OR 1.34, p = 0.006), CD8 T cell (OR 0.999, p = 0.024) and CD4 T cell (OR 0.995, p = 0.016) were independent risk factors for disease severity in patients with SARS-CoV-2 Omicron BA.2 variant infection." (PMID 37217986, 2023). "A significant correlation between increased circulatory IL-18 and decreased CD4 count suggests that IL-18 can be considered a potential biomarker of disease progression at the acute stage of infection." (PMID 36851142, 2023). "Vaccination in our infection naïve study cohort induced comparable frequencies of polyfunctional activated CD4+CD154+CD137+ T cells in all groups." (PMID 36932291, 2023). "This suggests that a replication-competent virus was present early after infection, and that CD4+ T cells from the case supported HIV replication indicative of the absence of any intrinsic viral restriction factors." (PMID 37702421, 2023).